SEMA3C (semaphorin 3C)
Diseases named in the same sentence as SEMA3C in open-access papers (continued):
Sharing a sentence is not in itself a finding about the gene and the disease.
glioma (continued). "Similar results were shown in other study, where Sema3C mRNA expression was similar between lower-grade and higher-grade gliomas." (PMID 31726800, 2019). "Disruption of Nrp1 signaling by siRNA knockdown significantly inhibits proliferation of glioma cell lines phenocopying Sema3C knockdown." (PMID 29642487, 2018). "To determine the significance of the increased Sema3C protein expression in glioma, we analyzed the relationship between Sema3C protein levels and the clinicopathological features of glioma patients." (PMID 26032848, 2015). "Further investigation will be required to evaluate Sema3C value as a molecular marker of glioma prognoses." (PMID 26032848, 2015). "Western blot analysis was used for detection of Sema3C protein levels in 84 different grade glioma samples: 12 grade I astrocytomas, 30 grade II astrocytomas, 17 grade III astrocytomas, and 25 grade IV astrocytomas (glioblastomas)." (PMID 26032848, 2015). "The analysis of the obtained data demonstrated that levels of Sema3C protein in glioblastoma (grade IV) were significantly higher than those of the lower grade (I–III) glioma tissues (p < 0.0001)." (PMID 26032848, 2015). "For example, Laffaire and colleagues by using genomic methylation and comparative gene expression profiles found that SEMA3C gene is differentially methylated in both low-grade gliomas and glioblastomas compared with normal brain controls." (PMID 26032848, 2015). "Expression of Sema3C in those cells has been demonstrated to be important for growth and invasion of the glioma tumor." (PMID 26032848, 2015). "With regard to Sema3C expression in gliomas, one of the prominent studies on this topic reported high Sema3C mRNA expression in the majority of the tested glioma cell lines and primary glioma cell cultures derived from surgically removed tumor tissue." (PMID 26032848, 2015). "“Low” protein levels of Sema3C were determined in 22 (26.2 %), “medium” Sema3C levels were determined in 41 (48.8 %), and “high” Sema3C levels were determined in 21 (25.0 %) glioma tumors." (PMID 26032848, 2015). "Sema3C-mediated glioma progression is dependent on activation of the small GTPase Rac125." (PMID 37080989, 2023). "SEMA3C correlates with the severity of glioma: SEMA3C expression is markedly increased in grade IV human glioma tumor samples (glioblastomas) compared to grades I-III glioma samples and higher expression levels of SEMA3C were associated with poorer survival rate." (PMID 30759745, 2019). "The mechanism through which SEMA3C promotes glioma malignancy may be through promoting survival of glioma stem cells." (PMID 30759745, 2019). "Moreover, Sema3C promotes survival and invasion of glioma stem cells (GSCs) through Rac1 activation." (PMID 31726800, 2019). "SEMA3C signalling is hypothesized to be involved in promoting glioma malignancy based on the observation that human glioma cell lines express high levels of SEMA3C and its receptors." (PMID 30759745, 2019). "In glioblastoma, Sema3C functions as a survival and invasion cue for glioma stem-like cells (GSCs)." (PMID 29642487, 2018). "Furthermore, SEMA3C has recently been shown to promote tumorigenicity and survival of glioma stem cells." (PMID 29348142, 2018). "In gliomas, Sema3C and its receptors are overexpressed in human glioma cell lines." (PMID 29642487, 2018). "Sema3C mRNA levels in gliomas were analysed by real-time PCR." (PMID 26032848, 2015). "A very recent study has demonstrated that Sema3C signaling could play a role as a central regulator of glioma stem cell survival and glioblastoma progression via activation of the Rac1/NF-κB signaling pathway." (PMID 26032848, 2015). "We also examined how Sema3C mRNA levels reflect upon the survival of glioma patient." (PMID 26032848, 2015). "The role of Sema3C expression in gliomas is currently unclear." (PMID 26032848, 2015).
glioma (continued). "However, the validation of experimental data on SEMA3C with the TCGA (The Cancer Genome Atlas) glioblastoma data set revealed different pattern of expression and methylation of SEMA3C, thus, leaving the question regarding SEMA3C expression in gliomas open." (PMID 26032848, 2015). "Sema3C mRNA values determined in 74 gliomas (9 grade I astrocytomas, 28 grade II astrocytomas, 13 grade III astrocytomas, and 24 grade IV astrocytomas) were normalized to mRNA levels of the β-actin-encoding gene ACTB, which has been used as an internal control." (PMID 26032848, 2015). "We observed a marked increase of Sema3C in glioblastomas compared to lower grade (i.e., WHO grades I, II, and III) astrocytomas indicating that the aberrant expression of Sema3C may be strongly associated with the advancement of glioma malignancy." (PMID 26032848, 2015). "The notion that Sema3C processing may differ between glioma grades is at some extent supported by our observation that a short, approximately 45 kDa fragment, which was recognized by Sema3C antibody in immunoblots, appeared more often in grade I-III astrocytoma samples rather than in glioblastomas." (PMID 26032848, 2015). "RGMB, EDN1, SEMA3C and NRTN have been indicated to regulate olfactory neurogenesis, mesenchymal stem cells regeneration, tumorigenicity of glioma stem cells and neurite outgrowth, respectively." (PMID 35511361, 2022). "For semaphorin 3C, SEMA3C, a gene overexpressed in glioma and employed by glioma stem cells to promote tumorigenicity, we observe 14 NCCMs (in 11 patients; one or more NCCM/patient) with an equal distribution of intergenic and intronic NCCMs (7 each)." (PMID 32513296, 2020). "An interesting observation was that SEMA3C and SEMA3F were statistically more expressed in glial tumours from men than from women, suggesting a possible hormonal regulation of these genes." (PMID 18781179, 2008). "For example, it was reported that the functional complex of SEMA3C with its receptors NRP1/PLXNA2/PLXND1 could activate Rac1/NF-κB signaling to promote the survival and migration of glioma stem-like cells." (PMID 32640719, 2020). "However, it is not clear if the high amount of Sema3C protein represents a functionally active form since the degraded products were detected in immunoblots in glioma specimens." (PMID 31726800, 2019). "Differences in Sema3C protein expression were not significant between grade I, II and III gliomas according to the Kruskal-Wallis test (p > 0.05)." (PMID 26032848, 2015). "Importantly, Sema3C mRNA expression was not increased in GBM samples, compared to lower grade gliomas." (PMID 31726800, 2019).
glioblastoma (17 papers, 2012 to 2024). The most malignant astrocytic tumor (WHO grade IV). "For example, SEMA3C is one of the top 20 most frequently altered genes and its expression is markedly increased compared to astrocytoma tissues and this increase was significantly associated with the shorter overall survival of patients in glioblastomas." (PMID 35785187, 2022). "Among the class 3 semaphorins, SEMA3C is notable for its frequent association with tumor progression and poor prognosis across multiple tumor types including lung, breast, gastric, and ovarian cancers as well as glioblastoma." (PMID 29348142, 2018). "In a mouse model of glioblastoma, combined depletion of Sema3C and β-catenin partner TCF1 extended animal survival more than single target inhibition alone." (PMID 37080989, 2023). "In later stages of life, semaphorin 3C overexpression is involved in multiple cancer types, including glioblastoma, lung, gastric, ovarian, and prostate." (PMID 34270956, 2021). "The anti-angiogenic activity of Sema3C was shown by overexpressing Sema3C in U87 glioblastoma cells and assessing formation of neovasculature in chick chorioallantoic membranes (CAM)." (PMID 32210960, 2020). "To achieve this goal, on the basis of glioblastoma U87 MG cells we constructed Sema3C-overexpressing stable cell line U87t-Sema3C, which we tested in the CAM model." (PMID 31726800, 2019). "In glioblastoma, Sema3C-positive cells were found in the perivascular niche where GSCs are known to reside." (PMID 29642487, 2018). "Analysis of human brain tumor samples revealed that Sema3C protein levels are markedly increased in glioblastoma (grade IV) compared to grade I–III astrocytomas, and this increase in Sema3C expression was associated with shorter survival time." (PMID 29642487, 2018). "Specifically, the SEMA ligand SEMA3C controls glioblastoma stem cell survival though RAC1 activation, suggesting that the effect of SEMA genes on brain tumor stem cells is cell context specific." (PMID 29377567, 2018). "Sema3C is overexpressed in 85% of glioblastoma and its receptors PlexinA2 and PlexinD1 are detected in all glioblastoma specimens analyzed." (PMID 29642487, 2018). "As Sema3C signaling has been implicated in GSC maintenance, we will focus our discussion on its receptors in glioblastoma." (PMID 29642487, 2018). "One family member, Semaphorin 3 C (SEMA3C), has been implicated in prostate, breast, ovarian, gastric, lung, and pancreatic cancer as well as glioblastoma." (PMID 28904399, 2017). "In the same laboratory, a microarray anaylsis of glioblastoma tissues revealed that Sema3C was overexpressed in a subpopulation of tumor cells in 30 out of 35 (85.7 %) cases but was barely detectable in normal brain tissue." (PMID 26032848, 2015). "The results demonstrated that protein levels of Sema3C were markedly increased in glioblastomas compared to grade I-III astrocytoma tissues and were significantly associated with the shorter overall survival of patients." (PMID 26032848, 2015). "Experiments conducted by Man and colleagues showed strong Sema3C staining compared to normal human brain tissue in a subpopulation of glioblastoma cells." (PMID 26032848, 2015). "In human glioblastoma, Sema3C expression and Wnt pathway activation were highly concordant." (PMID 37080989, 2023). "Since Sema3C is frequently overexpressed in glioblastoma, Sema3C signaling may be a significant mechanism of resistance to upstream Wnt pathway inhibitors." (PMID 37080989, 2023). "As we found previously that Sema3C has a tumor-inhibiting activity by suppressing tumor-associated angiogenesis processes on CAM model and this effect was even stronger with NaVP, we wanted to evaluate the cytotoxicity of NaVP on glioblastoma cells." (PMID 31726800, 2019).
glioblastoma (continued). "To evaluate the role of Sema3C in gliomagenesis and angiogenesis processes, we generated a stable U87t-Sema3C cell line on the basis of the glioblastoma U87 MG cells, which express Sema3C and yellow fluorescing protein Venus in a tetracycline-inducible manner (Section 4)." (PMID 31726800, 2019). "Additionally, Sema3C has been found to be one of the top 20 most frequently altered genes in glioblastoma." (PMID 29642487, 2018). "Together, these data suggest that targeting Sema3C in glioblastoma may have a favorable therapeutic ratio." (PMID 29642487, 2018). "Our studies suggest that Sema3C could be a promising target for glioblastoma treatment." (PMID 31726800, 2019). "We have found that SEMA3C stimulates EGFR and MET signaling in a broad range of cancer cell lines including bladder, and renal cancer as well as glioblastoma, suggesting that SEMA3C may be an important growth factor for a broad spectrum of cancers in addition to PCa." (PMID 29348142, 2018). "In this study, we constructed a stably overexpressing Sema3C glioblastoma cell line U87 MG and tested it on the chicken embryo chorioallantoic membrane (CAM) model with the aim to reveal Sema3C protein function on angiogenesis process in ovo." (PMID 31726800, 2019). "To determine if class-3 semaphorins have the potential to be used as drugs for the treatment of brain cancer we expressed all the recombinant semaphorins, with the exception of sema3C, in U87MG glioblastoma derived cells." (PMID 22936999, 2012). "For example, SEMA3C is selectively expressed in Glioblastoma stem cells but not in their counterpart neural progenitor cells or non-stem tumor cells." (PMID 35785187, 2022). "In glioblastoma, Sema3C was selectively expressed in GSCs but not in their counterpart neural progenitor cells or non-stem tumor cells." (PMID 29642487, 2018). "Hence, we screened a panel of cells lines representing renal cancer (CAKI‐1, CAKI‐2, ACHN), bladder cancer (UC13, T24), and glioblastoma (U87MG), for expression of SEMA3C, EGFR, MET, Plexin B1, Plexin D1, NRP1, and NRP2." (PMID 29348142, 2018). "In glioblastoma, Sema3C does not appear to be expressed in neural progenitor cells, yet is highly expressed in GSCs." (PMID 29642487, 2018).
gastric cancer (12 papers, 2015 to 2025). A primary or metastatic malignant neoplasm involving the stomach. "SEMA3C, a secreted glycoprotein of the semaphorin class 3 family, has been implicated in gastric cancer progression." (PMID 39408230, 2024). "SEMA3C also enhanced endothelial cell adhesion and stimulated angiogenesis in gastric cancer tissues by activating integrin phosphorylation and promoting vascular endothelial growth factor 120 secretion." (PMID 36277723, 2022). "In gastric cancer, SEMA3C is highly expressed in neoplastic tissue compared to normal surrounding tissue, and knockdown of SEMA3C suppresses primary gastric tumor growth as well as metastasis to the liver and reduced microvessel density." (PMID 30759745, 2019). "Recent studies have shown that Sema3C is critical for gastric cancer angiogenesis; on the other hand, Sema3 acts as an inhibitor of pathological retinal angiogenesis." (PMID 30304095, 2018). "Recent study on gastric cancer cells provided yet another evidence that Sema3C assists tumor progression." (PMID 26032848, 2015). "Additionally, to investigate the clinical relevance of the target gene expression in gastric cancer, we examined their expression levels at different stages of TCGA gastric cancer samples and observed significantly higher expression of SERPINE1, COL5A2, SEMA3C and LOXL2 in more aggressive stages." (PMID 36307405, 2022).
pancreatic cancer (9 papers, 2017 to 2024). "SEMA3C can be used as a novel target or marker with therapeutic or diagnostic potential in pancreatic cancer especially in tumors harboring the specific KRAS G12D mutation." (PMID 35785187, 2022). "High expression of SEMA3C in patients was significantly associated with the decreased survival of pancreatic cancer patients based on the TCGA database." (PMID 35785187, 2022). "The study indicates that SEMA3C is a potentially promising and attractive target for pancreatic cancer therapy especially in patients with a G12D mutation in KRAS." (PMID 35785187, 2022). "We discovered a gene named SEMA3C was highly expressed in pancreatic cancer cell lines and patients with a G12D mutation in KRAS." (PMID 35785187, 2022). "Consistent with the previous observations, high SEMA3C expression in pancreatic cancer was linked with a shorter survival time based on the analysis of the TCGA database." (PMID 35785187, 2022). "Here, we found that SEMA3C was highly expressed in pancreatic cancer and associated with the KRAS G12D mutation." (PMID 35785187, 2022). "Similarly, it has been found that aberrant SEMA3C expression is associated with poor survival of pancreatic cancer patients." (PMID 31649890, 2019). "Taken together, this raises the possibility that SEMA3C signalling may have a role in maintaining the oncogenic effects of KRAS mutations in pancreatic cancer." (PMID 30759745, 2019). "SEMA3C expression is higher in pancreatic cancer than in normal tissue, positively correlated with tumor stage, and inversely correlated with patient survival." (PMID 38321460, 2024). "SEMA3C played a significant role in cell growth, cell colony formation, cell cycle arrest, and the increased apoptosis or necrosis of pancreatic cancer cells." (PMID 35785187, 2022). "Next, we found that SEMA3C overexpression or inhibition can significantly regulate the expression of the autophagy-related markers in pancreatic cancer lines." (PMID 35785187, 2022). "As expected, SEMA3C was highly expressed in pancreatic cancer, compared to paired normal tissue in three pancreatic cancer cohorts from TCGA/GSA/Oncomine." (PMID 35785187, 2022). "To explore the role of SEMA3C in pancreatic cancer in vivo, we created a KPC tumor model by subcutaneously injecting 5×105 mouse KPC-Luc cells into C57/BL6 mice (Charles River)." (PMID 35785187, 2022). "SEMA3C expression is positively correlated with the clinical stages of pancreatic cancers, while patients with advanced stages of pancreatic cancer have a significantly shorter survival rate." (PMID 35785187, 2022). "SEMA3C regulated the autophagy process and tumor immune microenvironment, which in turn promoted pancreatic cancer cell growth." (PMID 36601127, 2022). "In pancreatic cancer cells, SEMA3C knockdown or inhibition exhibited growth/colony inhibition and cell cycle arrest." (PMID 35785187, 2022). "We then examined the correlated expression of both PD-L1 and SEMA3C in pancreatic cancer with TCGA data by Timer software." (PMID 35785187, 2022). "Inhibition of SEMA3C with the SEMA3C special inhibitor 3,5,4’-Tribromosalicylanilide resulted in cell cycle arrest and apoptosis increase in pancreatic cancer cell lines." (PMID 35785187, 2022). "SEMA3C promotes tumor growth and metastasis in pancreatic cancer by activating the ERK 1/2 signaling pathway." (PMID 35785187, 2022). "SEMA3C is upregulated in pancreatic tumor tissue compared to normal tissue, and SEMA3C expression within pancreatic tumors is associated with a more advanced TNM classification of malignant tumors (TNM) stage and decreased one-year survival." (PMID 30759745, 2019). "The Schematic illustration of probable mechanism of SEMA3C role in pancreatic cancer." (PMID 35785187, 2022). "SEMA3C regulates the autophagy process and enhances the tumor immunosuppressive related genes expression of macrophage, thus targeting the SEMA3C is a promising target in pancreatic cancer therapy." (PMID 35785187, 2022).